PIR (pirin)
Diseases named in the same sentence as PIR in open-access papers (continued):
Sharing a sentence is not in itself a finding about the gene and the disease.
cancer (continued). "Similarly, piR-823 increases glucose-6-phosphate dehydrogenase (G6PD) expression, which in turn increases the consumption of glucose by cancer cells while decreasing the amount of intracellular reactive oxygen species (ROS)." (PMID 39102033, 2025). "In addition, Pirin mediates breast tumorigenesis by promoting E2F1 expression, a key cell cycle regulator that is abnormally active in malignant tumors." (PMID 33557375, 2021). "This novel function of piR-hsa-211106 in LUAD cells might serve as an example for studies on piRNAs and human cancers." (PMID 34249688, 2021). "We then examined whether such function of cell cycle arrest has impact on cancer cell growth in vivo and found that the growth rates of MCF7 and ZR75–1 xenografts overexpressing piR-36,712 were significantly slower than those of control counterparts." (PMID 30636640, 2019). "As our understanding of biological pathways regulated by HSF1 in supporting cancers deepens, such as the role of the PIKK family, CDK9, and Pirin in the inhibition of the HSF1 stress pathway, identification of new chemotypes as potential candidate for cancer therapy will be easier." (PMID 30356024, 2018). "Only recently it was reported that pirin suppresses E-cadherin expression and is involved in the regulation of Snail and Twist expression in HeLa cells, suggesting that pirin is involved in EMT and regulation of cancer metastasis." (PMID 29118270, 2017). "Unfortunately, the active form of vitamin D may influence the epigenetic mechanisms of HCC cells via piR-823 expression and may not be beneficial for as an anti-cancer in HCC patients (oner 2021)." (PMID 39102033, 2025). "Given PIR’s role in promoting EMT, investigating whether PIR-mediated EMT influences ferroptosis could offer valuable insights into the interplay between EMT and ferroptosis in cancer progression." (PMID 39534872, 2024). "PIR played a negative role in regulating ferroptosis in multiple cancer cells." (PMID 36467089, 2022).
infection (5 papers, 2009 to 2026). The state of being infected such as from the introduction of a foreign agent such as serum, vaccine, antigenic substance or organism. "To assess potential pIR function, we explore SNP associations to bioclimatic variables and to bacterial levels after infection with the causative agent of Pierce’s disease (Xylella fastidiosa)." (PMID 34479604, 2021). "By immunofluorescence assay and western blot analysis with mass spectrometry, both S7 and L1 PIR proteins are detected in iRBC; S7s are located as discrete foci in the cytoplasm of iRBC at the acute-phase of infection." (PMID 35782145, 2022). "Localisation pattern of PIR proteins identified in proteome analyses of fractionated samples prepared from P. chabaudi infected erythrocytes at the acute phase of infection." (PMID 35782145, 2022). "Localisation pattern of PIR proteins identified in proteome analyses of fractionated samples prepared from P. chabaudi infected erythrocytes at the chronic phase of infection." (PMID 35782145, 2022). "In the silkworm-BmNPV infection system, it was found that piR-bmo-796514, a host-derived piRNA, could be significantly induced in larval fat body and BmN cells and could target and inhibit the expression of E3 ubiquitin ligase RNF181." (PMID 41494040, 2026). "However, overexpression of RNF181 or treatment with piR-bmo-796514 inhibitor in BmN cells prevented the induction of Integrin α2b-like expression by BmNPV infection at 12 and 24 hpi." (PMID 41494040, 2026). "Here, we demonstrated that infection by Bombyx mori nucleopolyhedrovirus (BmNPV), a large DNA virus, induced significant upregulation of silkworm host piR-bmo-796514, which facilitated viral proliferation by suppressing the expression of E3 ubiquitin ligase RNF181." (PMID 41494040, 2026). "We found that most PIR proteins are co-expressed in clusters during acute and chronic infection; members of the S7 clade are predominantly expressed during the acute-phase, whereas members of the L1 clade dominate the chronic-phase of infection." (PMID 35782145, 2022). "P. chabaudi schizonts are sequestered during the infection in mice, and can only be obtained after a period of in vitro culture, which may affect the detection of PIR at that stage and improving the culture of P. chabaudi would clarify PIR expression at this stage of parasite development." (PMID 35782145, 2022). "Involvement of Pirin signaling in actin cytoskeleton reorganization, phagocytic cup formation, and interaction with actin filament modulating proteins suggest association of excessive Pirin production with the development of neurological complications, in presence or absence of infection." (PMID 38033031, 2023). "In conclusion, there does not seem to be an exclusive subcellular compartment where PIR proteins are localised during both the acute- and chronic-phases of infection." (PMID 35782145, 2022). "In this study, utilizing the silkworm as a model organism, we have focused on a host derived piRNA, piR-bmo-796514, which was significantly induced by Bombyx mori nucleopolyhedrovirus (BmNPV) infection and could promote (rather than inhibit) the proliferation of exogenous DNA viruses." (PMID 41494040, 2026).
neurodegenerative disease (2 papers, 2022 to 2023). A disorder of the central nervous system characterized by gradual and progressive loss of neural tissue and neurologic function. "It appears that Pirin is associated with a myriad of inflammatory and neurodegenerative diseases as well as metastasis of cells through interaction with other proteins." (PMID 38033031, 2023). "In our study, we have demonstrated Pirin protein to have role in multiple important processes including inflammation, rearrangement of actin cytoskeleton as well as metastasis, ischemic attack and neurodegenerative diseases among others." (PMID 38033031, 2023). "piR-hsa-2834636 is derived from HBA2, of which the mRNA is dysregulated in the frontal cortex of neurodegenerative disease." (PMID 35269612, 2022).
endocrine system diseases (1 paper, 2023). "Pirin, RELA (p65) and NFKBIA are significantly associated with endocrine system diseases." (PMID 38033031, 2023).
PIR also shares sentences with these, for which no sentence is quoted: glioblastoma (2 papers); non-small cell lung carcinoma (2); squamous cell carcinoma (2); acute myocardial infarction (1); adenocarcinoma (1); adenoma (1); allergic rhinitis (1); amyotrophic lateral sclerosis (1); breast tumors (1); cardiopulmonary disease (1); chronic hepatitis (1); chronic obstructive pulmonary disease (1); clear cell renal cell cancer (1); colitis (1); colon adenoma (1); head and neck squamous cell carcinoma (1); Hepatitis B (1); HIV-1 infection (1); hyperplasia (1); kidney tumor (1); leprosy (1); liver cancer (1); liver fibrosis (1); lung diseases (1); metabolic disease (1); metastatic melanoma (1); motor neuron disease (1); myocardial ischemia (1); nevus (1); Parkinsonism (1).
A further 9 diseases each share a sentence with PIR in 1 paper.